IFIT1 (interferon induced protein with tetratricopeptide repeats 1)
Diseases named in the same sentence as IFIT1 in open-access papers (continued):
Sharing a sentence is not in itself a finding about the gene and the disease.
infection (continued). "Most cell subsets had elevated scores after FA-S infection, especially three subclusters of macrophages (Macro-C1qa, Macro-Saa3, and Macro-Ifit1), indicating that these cells are the main source of the inflammatory cytokine storm." (PMID 36566328, 2022). "Before infection, the cis-element was linked to IFIT1B and IFIT5, which were dynamically reshuffled to link with IFIT1, IFIT2, and IFIT3 after infection." (PMID 36195603, 2022). "The expression heatmaps of the endothelial cell genes in the sample revealed that DCN and IFN-activated endothelial cell marker genes (Irf8, Rsad2, Ifit1, Ifit3, Iigp1) were significantly upregulated at 1 month post-infection as compared with the WT group." (PMID 36569953, 2022). "Both VSV and EMCV infections cause neuroinvasive disease and induce IFN-β, IFIT1, and IFIT2 in the brain." (PMID 36325336, 2022). "It revealed that the expression of RIG-1, MDA5, and MxA was not increased after 2 and 3 weeks from the onset the disease, while for IFIT-1 it was observed the second peak at 21 day post infection." (PMID 36298646, 2022). "Two different interferon-stimulated genes, Ifit1 and Oasl2, were next examined and shown to be more strongly induced, 300-fold and 1200-fold, respectively, upon infection, as expected from previous RNAseq data." (PMID 36560642, 2022). "In the present study, strong up-regulation of Ifit1 transcript levels was also observed upon infection with MCMV, an effect which was significantly reduced by TAT-I24 2 h post-infection." (PMID 35806257, 2022). "Following transfection with specific siRNAs against IFIT1 or Mx1 (siIFIT1, siMx1) and subsequent infection with HCMV for 48 h, we achieved a ~60% reduction in IFIT1 protein expression and near to complete silencing of Mx1 protein." (PMID 34162877, 2021). "Upon infection with R. equi, cGAS KO macrophages had reduced levels of Ifnb, Isg15 and Ifit1 transcripts, and a significant but less dramatic reduction in Tnfa." (PMID 34473814, 2021). "It has been described that various stimuli, such as infection with viruses or viral and bacterial molecular patterns, have been shown to directly induce transcription of the IFIT1/ISG56 family." (PMID 34722780, 2021). "Levels of ISG mRNAs were variable, with SARS-CoV-2 inducing moderate levels of OAS2 and IFIT1 mRNAs, but only late in infection (48 hpi), similar to those induced by SINV at 24 hpi." (PMID 33811184, 2021). "SARS-CoV-2 failed to significantly alter the levels of any tested genes except for IFIT1, where a significant decrease in the mRNA levels was noted upon infection." (PMID 34006825, 2021). "This resulted in significant silencing of MX1 and IFIT1 at 48 h post-infection (72 h post-transfection) that remained up to 96 h post-infection." (PMID 34079533, 2021). "To investigate, SC were pretreated with 5 pg/mL (1 IU/mL) of recombinant human IFN-β for 24 h prior to infection (MOI 1) and ZIKV replication as well as MX1 and IFIT1 expression were then evaluated by RT-qPCR at 48 h post-infection." (PMID 34079533, 2021). "Genes encoding interferons (Ifnb, Ifnl2 and Ifnl3), chemokines (Ccl7, Ccl5, and Cxcl10), and ISGs (Ifit1, Ifit2, Ifit3b, Oas3, Ifi44, Rsad2, and Isg15, among others) were prominently represented among those induced by infection in Ifnar1-/- mice." (PMID 34591933, 2021). "We noted a strong upregulation of genes encoding for CXCL2, CXCL3, CXCL10, IFNβ-1, IFNλ-1, -2, -3, endothelin 1 (EDN1) and IFIT-1, -2, -3 following E-30 infection." (PMID 32872518, 2020). "Although IFN-α pretreatment of A549-ISG15−/− cells renders them resistant to infection, when IFIT1 was also knocked down, PIV5 infection was restored." (PMID 32423918, 2020). "At 2 days after infection, the levels of Ifit1 mRNA were higher in the brains (P < 0.0001 versus WT/G32S) and spinal cords (P < 0.001 versus WT, P < 0.0001 versus G32S) of mice infected with Y114A." (PMID 32047134, 2020).
infection (continued). "To test this possibility, we measured expression of Ifnb and the interferon stimulated genes viperin and Ifit1 in mice brains following intravenous infection." (PMID 32636381, 2020). "We used qPCR to measure the gene expression of the NF-κB–activated genes IL-8 and IL-6 as well as the interferon-stimulated genes (ISGs) IFIT1 and IFIT2 in MyD88-deficient cells and MyD88-intact cells during DENV2 infection." (PMID 32117091, 2020). "The expression of IFNB1, ISG15, and IFIT1 mRNA were decreased in HEK293 cells transfected with Parkin upon infection with SeV." (PMID 32983119, 2020). "In this experiment, doses of VLP required to suppress IFIT1-luc expression were high, equivalent to a multiplicity of infection of 20 as measured by correlating VLP reverse transcriptase levels (SG-PERT), with HIV-1 GFP titers on THP-1." (PMID 33300875, 2020). "We also investigated infection of these cell lines with other paramyxoviruses whose sensitivity to IFIT1 has been previously reported." (PMID 32423918, 2020). "By contrast, infection of mCherry-Ifit1-transfected cells was similar to infection of empty vector–transfected cells, indicating that Ifit1 does not inhibit MHV infection in these cells." (PMID 33454014, 2020). "Later in infection, when IFIT1 is highly expressed in the cytoplasm, IFIT1 prevents induction of type I IFN by interfering with MAVS signalling." (PMID 31372503, 2019). "Infection of Ifit1-/- cells resulted in up to 20x higher MNV-1 yields compared to wild-type cells over the course of the infection, suggesting that Ifit1 has antiviral activity during norovirus infection." (PMID 31372503, 2019). "IFIT1 was significantly increased only during infection with RESTV, with the greatest abundance observed at 72 h." (PMID 31689981, 2019). "The discrepancy between viral and IFIT1 protein abundance was especially apparent upon infection with IAV-ΔNS1." (PMID 31856218, 2019). "SCs responded to infection with increased expression of mRNAs for IFNβ, IFNλ, IFIT-1, Mx1, NLRP3, IL-23A, IL-6 and TNFα." (PMID 31289325, 2019). "As expected, infection with rTHOV-ΔML and rTHOV-SW elicited expression of IFIT1 and IFIT3, whereas their expression in rTHOV-wt sample was ~50 fold lower." (PMID 29709033, 2018). "In contrast to COP, infection with vv811 triggered ∼7-fold increase in IFIT-1-driven GLuc activity, suggesting that the absence of immunomodulatory genes limits the ability of vv811 to block IRF-3 responses in differentiated THP-1 cells." (PMID 29491158, 2018). "Detection of IFN-induced proteins with tetratricopeptide repeats 1 (IFIT1) by immunoblot confirmed the efficient induction of an antiviral response during the timeframe of the infection." (PMID 29385716, 2018). "We also investigated IFIT1 mRNA levels by mRNA FISH confirming that the number of IFIT1 transcripts was increased in Δvhs infected cells compared to mock or 12-hour Wt infection (IFIT1)." (PMID 30475899, 2018). "Nevertheless, several downstream genes of the type I IFN signaling pathway were elevated, consistent with reports of other New World arenavirus human infection, including Ifi27, Ifi27l2b, Ifi44, Ifi204, Ifit1, Mx1 and Mx2." (PMID 29724035, 2018). "We show that infection with live bacilli specifically alters the expression of host genes such as Rsad2, Ifit1/2/3 and Rig-I, whose potential roles in resistance to M. tuberculosis infection have not yet been investigated." (PMID 28176867, 2017). "Mx1 and Ifit1 mRNA expression increased in MLN on days 2 to 5 after infection, compared to controls." (PMID 27405244, 2016). "We found that infection with the IFN-sensitive RRV strain resulted in the robust induction of several well-defined ISGs, including those encoding IFIT1/2/3, ISG15, ISG20, RSAD2, and Mx2." (PMID 27128797, 2016). "In control HEK 293T cells transduced with a non-target sequence shRNA (shNT)-expressing lentivirus, SeV protein was only detectable at 24 hours post-infection which coincided with IFIT1 induction." (PMID 27454487, 2016).
infection (continued). "Nod1 (C10) and its responsive genes Irf7 and Stat1 (C11) were elevated late during infection as well as interferon-induced genes Cxcl10, Ifit1-3, Iigp1 and Rsad2 (C7)." (PMID 26367386, 2015). "IFIT1 binds to the free 5′-ppp moiety on RNA of a number of viruses, including influenza A virus, and inhibits infection by forming a complex with IFIT2 and IFIT3 that sequesters viral nucleic acid." (PMID 25191744, 2014). "In contrast, infection with EMCVΔL lacking both L protein and EMCV L region RNA induced lower levels of Ifnb1 or Ifit1 than infection with EMCV ZnC19AC22A at two different multiplicities of infection (MOI)." (PMID 24550253, 2014). "Because a deficiency of Ifit1 did not significantly alter pathogenesis of WNV-WT, we conclude that 2′-O methylation of the 5′ viral RNA cap by the NS5 largely overcomes Ifit1-mediated restriction of infection." (PMID 22589727, 2012). "Our studies suggest that lethal phenotype after WNV-E218A infection by the intracranial route in Ifit1−/− mice was due to both cell-intrinsic and extrinsic mechanisms." (PMID 22589727, 2012). "Our peripheral and intracranial infection studies with WNV-E218A in Ifit1−/− mice are more consistent with a model in which direct infection of endothelial cells contributes to CNS spread." (PMID 22589727, 2012). "However, alphaviruses have evolved molecular strategies to circumvent IFIT1-mediated restriction and facilitate infection in mammalian cells." (PMID 42043228, 2026). "Additionally, ROC and logistic regression analyses revealed that the combined expression of IFIT1 and RSAD2 effectively distinguishes HPV16 and GV infections, underscoring their diagnostic value." (PMID 40510586, 2025). "Initially, IFIT1 production might surge temporarily to combat infection, but as viral plasmids stabilize within the cells over time, leading to the establishment of a mature immune evasion mechanism, IFIT1 expression could be suppressed." (PMID 40510586, 2025). "However, the ~100-fold increase in virus titre seen in IFN-pre-treated cells when IFIT1 is knocked out would suggest that there is a large fitness cost to the virus during infection." (PMID 40146622, 2025). "Protein–protein interaction network analysis identified several hub genes (Usp18, Stat2, Ifih1, Jun, Irf7, Rsad2, Ifit1, Mx1) that likely play central roles in coordinating the antiviral immune response and immunometabolic regulation across different phases of infection." (PMID 40867782, 2025). "Finally, at 72 hours post-PIV3 infection, the transcriptional response remains interferon-centric, with continued expression of IFIT1, IFIT2, IFIT3, MX1, and OAS2." (PMID 39591472, 2024). "Whether mosquitoes possess a receptor or protein able to discriminate between cap1 and cap0 similar to RIG-I or IFIT1 in vertebrates and whether it is constitutively expressed or upregulated upon infection like ISGs in vertebrates remains to be investigated." (PMID 39356716, 2024). "Finally, at 72 hours post-PIV3 infection, the transcriptional response remains robust and interferon-centric, with continued expression of IFIT1, IFIT2, IFIT3, MX1, and OAS2." (PMID 39591472, 2024). "Importantly, a CMV-driven reporter gene showed constant transcription rates throughout infection, indicating that reduced IFIT1 transcriptional activation at later timepoints in infection was not due to global virus-induced transcriptional inhibition." (PMID 37814072, 2023). "While interferons and interferon-inducible proteins like IRF7, IFIT1, and IFIT3 are primarily associated with antiviral defence, they can also be induced in response to bacterial ligands, contributing to the resolution of the infection." (PMID 37845774, 2023). "For this, we classified IFIT1+ infections as replicating either ‘fast’ or ‘slow/intermediate’ on the basis of split-GFP intensity time traces using the clustering algorithm described before and determined the average IRF3-BFP nuclear translocation for both groups." (PMID 37814072, 2023).
infection (continued). "Finally, the increase we observed in IFNβ-mediated IFIT1 expression following ΔospC1/C3 or ΔospC1/C3, pB infection was ablated in cells depleted for CaM." (PMID 35568036, 2022). "During E30 infection, genes associated with the type I IFN signaling pathway (Isg15, Mx1, Mx2, Sp100, Ifit1, Ifit3, Ifih1, Irf7, Irf9, guanylate-binding proteins 2 [Gbp2], and Stat1) and defense response to viruses (Ddx58, Ddx60, Zbp1, Oas2, Nlrc5, and Eif2ak2) were significantly upregulated." (PMID 36147849, 2022). "However, other proteins such as ISG15, Nitric Oxide Synthase 2 (NOS2), IL1-β and IFIT1 were similarly altered in both conditions upon infection." (PMID 36131943, 2022). "As previously observed, infection with WT bacteria inhibited expression of Viperin and IFIT1." (PMID 35568036, 2022). "However, a number of genes involved in antiviral defense, inflammatory response, and IFN pathways (i.e., CXCL10, CXCL11, IFIT1, etc.)were commonly upregulated in infected Vero E6 cells and HBECs at later stages of infection." (PMID 35604092, 2022). "To investigate whether MX1 and IFIT1 actively antagonize ZIKV propagation in SC, we next transfected SC with either MX1 or IFIT1 siRNA 24 h prior to infection (MOI 1)." (PMID 34079533, 2021). "IFIT1-Luc was measured 6, 8, and 24 hr after cGAMP addition/infection." (PMID 33300875, 2020). "Nevertheless, if ISG15-deficient cells were treated for longer periods with IFN-α prior to infection, they did become resistant, even when IFIT1 was knocked down, suggesting that at later times, the inhibition of protein synthesis was the principal cause of resistance." (PMID 32423918, 2020). "We conclude that viral DNA is the active PAMP and this notion was also supported by the observation that mutation D185E in the RT active site (HIV‐1 ∆CA‐SP1 RT D185E) also reduced activation of IFIT‐1 luc expression and CXCL10 secretion on infection of the THP‐1 IFIT‐1 reporter cells." (PMID 32852081, 2020). "Using luciferase reporter hepatitis C virus (Jc1-HCVcc) infection model and the induction of MxA and IFIT1 as readouts, we determined the treatment conditions for subsequent functional experiments as follows: 1 ng/mL for IFNα2b and 25 ng/mL for IFNλ1 and both for 8–24 h." (PMID 31379885, 2019). "Studies using herpes simplex virus type 1 (HSV-1) demonstrated that IFIT1 expression could be driven by infection even in the presence of CHX in human fibroblasts (HFs) but could not be detected in the human epithelial osteosarcoma cell line U2OS." (PMID 31921100, 2019). "Levels of mRNAs for IFNβ1 and IFN response gene proteins Mx1, a GTPase induced by type I and type III IFNs38, and IFN-induced protein with tetratricopeptide repeats (IFIT)-1 were upregulated after infection with both YFV and ZIKV with the greatest response induced by YFV." (PMID 31289325, 2019). "Expression of TLR2 and IFIT1 was also significantly higher in CL lesions, suggesting that these molecules maybe differentially modulated at the infection site, compared to PBMCs." (PMID 27870860, 2016). "In contrast, expression of other genes in the IFN signaling pathway (G1p2, Ifi35, Ifit1 and Stat2) were shown to be higher in the infected WT as compared to the infected Ifnar1-/- mice after days 2 and 3 of infection, when the bacterial load was lower in the infected Ifnar1-/- mice." (PMID 26918359, 2016). "STAT1 and IFIT1 upregulation has previously been seen in proteomic analysis of HeLa cells infected with reovirus, suggesting that despite low concentration of LPS, the 3T3-L1 adipocytes exert the same stress-response as during infection." (PMID 27438462, 2016). "Interestingly, a more rapid decline of the IFNB1 mRNA level is observed at 48 hours post-infection compared to IFIT1 and TNF mRNA levels, which remained higher at this time point." (PMID 23785285, 2013).
infection (continued). "We observed cell-type specific differences in the ability of an Ifit1 deficiency to rescue replication of WNV-E218A; for example, WNV-E218A showed equivalently impaired infection in wild type and Ifit1−/− brain endothelial cells, which potentially allow virus access into the brain." (PMID 22589727, 2012). "Initial studies established that none of the primary cells deficient in Ifit1 sustained enhanced infection with WNV-WT compared to wild type cells (P>0.1) at any of the time points examined." (PMID 22589727, 2012). "Notably, we show that only OROV-P infection downregulates IFIT1 expression at 8-dpi." (PMID 40964022, 2025). "We infected 293T cells with these SeV variants at five different multiplicities of infection (MOIs) and evaluated RIG-I and IFIT1 fold induction after 2 days at 34°C to determine if the reduction in ISG expression could simply be attributed to the P and/or L mutations attenuating viral growth." (PMID 39494910, 2024). "Interestingly, further examining IFIT1 transcriptional dynamics, we found that IFIT1 transcriptional activity was strongest when activated early in infection, with a ~3-fold higher activation level if activated at 5 h vs 10 h after initiation of vRNA replication." (PMID 37814072, 2023). "Importantly, a lower viral load was also observed in IFIT1+ cells upon infection with EMCV(LWT), indicating that heterogeneity in viral replication similarly affects the efficiency of antiviral response activation when the dsRNA sensing pathway is more efficiently inhibited." (PMID 37814072, 2023). "Therefore, we hypothesised that Ifit1 may mediate its antiviral activity during norovirus infection by promoting the innate immune response to infection." (PMID 31372503, 2019). "The observed differences in viral replication suggest that ISG20 may participate in orchestrating innate immune responses in particular cell types, which affects the outcome of infection with IFIT1-sensitive viruses, which are less able to evade host antiviral responses." (PMID 30232164, 2018). "However, IFIT1 induction was only detected at 48 hours post-infection." (PMID 27454487, 2016). "Indeed, IFIT1 KI/3 MEFs released high levels of IFN-β upon infection with viruses having wt 5’UTRs." (PMID 25927359, 2015). "We reasoned that four key parameters might vary between wildtype DENV and the E217A mutant: As the translation of mutant RNA is impaired because of its sequestration by IFIT1 both the viral production and, possibly, also the delay in virus production after infection could be altered." (PMID 26720415, 2015). "Thus, the failure of WNV-E218A to spread to the brain after peripheral inoculation could be due in part, to an Ifit1-independent restriction in BBB infection and virus crossing." (PMID 22589727, 2012). "As the subcutaneous infection experiments suggested tissue specific restriction of WNV-E218A by Ifit1, we hypothesized that the 2′-O methylation mutant might replicate less efficiently in the central nervous system (CNS), which would explain the attenuated phenotype." (PMID 22589727, 2012). "Moreover, a deficiency in Ifit1 did not result in productive infection of the kidney, an organ that is normally resistant to WNV infection in wild type mice yet permissive in animals with defects in type I IFN induction, signaling, or effector functions." (PMID 22589727, 2012). "Representative ISG mRNA levels (IFIT1, OAS2) were also increased during infection with the nsp15 mutant in MRC-5 cells, but were induced to a similar extent in nasal ALI cultures." (PMID 41369222, 2026). "In contrast, infection of A459ACE2 cells with NL63 robustly induced IFNB and IFNL1 as well as IFIT1 and OAS2 by 48 hpi." (PMID 41369222, 2026). "Of these genes, 6 (OASL, IFI27, IFIT1, IFIT3, RSAD2and IFI44L) were in protein-protein interaction network and at each stage of infection." (PMID 40255307, 2025).